HDAC4 (histone deacetylase 4)
Diseases named in the same sentence as HDAC4 in open-access papers (continued):
Sharing a sentence is not in itself a finding about the gene and the disease.
heart failure (17 papers, 2010 to 2025). Inability of the heart to pump blood at an adequate rate to meet tissue metabolic requirements. "CaMKIIδ deficient mice also showed reduced kinase activity towards HDAC4, which regulates stress-responsive cardiac gene expression and is protective against heart failure." (PMID 39596076, 2024). "For example, exercise-induced fragments of HDAC4 avert heart failure through the regulation of the hexosamine biosynthetic pathway, protein O-GlcNAcylation, and calcium handling." (PMID 40822014, 2025). "-Exercise-induced HDAC4 fragments protect against heart failure.-HDAC1/HDAC2 reverse diabetic heart pathology." (PMID 40822014, 2025). "The N-terminal proteolytically derived fragment of HDAC, HDAC4-NT, was observed to be lower in the hearts of mice with heart failure, and its expression was increased with exercise." (PMID 39596076, 2024). "It has also been reported that ABHD5 proteolyzes HDAC4 to maintain cardiometabolic homeostasis during pressure overload and lipotoxicity-induced heart failure." (PMID 39726946, 2024). "Establishing the mechanisms that determine HDAC4 localization in adult cardiomyocytes has significant translational implications due to the role of class II HDACs in the development of heart failure." (PMID 33590335, 2021). "Nuclear histone deacetylase 4 (HDAC4) represses MEF2-mediated transcription, implicated in the development of heart failure." (PMID 33590335, 2021). "Previous studies demonstrated that ABHD5 could activate AMPK to further proteolyze HDAC4 into the N-terminal polypeptide of HDAC4 (HDAC4-NT) to protect against heart failure." (PMID 38467717, 2024). "A previous study demonstrated that ABHD5 could further proteolyze HDAC4 into the N-terminal polypeptide of HDAC4 (HDAC4-NT) to protect against heart failure." (PMID 38467717, 2024). "In another study, mice with cardiac KO of HDAC4 developed heart failure in diabetes models (STZ or db/db), which was rescued by the expression of the N-terminal proteolytic fragment of HDAC4, suggesting that the N-terminal fragment of HDAC4 plays a role in protecting the diabetic heart from failure." (PMID 38983721, 2024). "Patients with heart failure and atherosclerosis have high levels of HDAC-4 expression." (PMID 38322766, 2024). "Baseline HDAC4 FNuc/FCyto was dramatically reduced in resting myocytes isolated from either failing rabbit hearts or 10–12 weeks old CaMKIIδC transgenic mice, for which we previously documented overt heart failure." (PMID 33590335, 2021). "Cardiac OE of HDAC4-NT (N-terminus) by intravenous injection of AAV9 with the cytomegalovirus (CMV)-enhanced myosin light chain promoter (Myl2) protected against the heart failure on TAC, suggesting that HDAC4-NT can promote cardiac function." (PMID 38983721, 2024). "HDAC4 prevents effective DNA binding by myocyte enhancer factor 2A (MEF2A, MEF2), contributing to hypertrophic gene expression and heart failure." (PMID 37326902, 2023). "Studies have shown that αV integrin receptor promotes the physiological effects of irisin, and that irisin can increase the survival rate of heart failure patients by upregulating ROS, lactate dehydrogenase (LDH), and histone deacetylase 4 (HDAC4)." (PMID 36135450, 2022). "In contrast, Kronlage and co-workers reported that HDAC4 silencing can develop heart failure in T1DM and T2DM, which indicates the protective role of HDAC4 in the diabetic heart." (PMID 34071497, 2021). "HDAC4‐KO mice developed heart failure in both type 1 and type 2 diabetes models, whereas wild‐type mice did not develop overt signs of heart failure, suggesting that HDAC4 protects diabetic hearts." (PMID 40497340, 2025). "One somewhat unexpected finding was that KN93 was less able to increase nuclear HDAC4 accumulation in failing vs. non-failing cells, because baseline CaMKII activation is increased in both heart failure models." (PMID 33590335, 2021).
heart failure (continued). "We next tested whether this PKA vs. CaMKIIδ disbalance at HDAC4 is altered in two animal models of heart failure; a non-ischemic rabbit heart failure model and CaMKIIδC transgenic mice." (PMID 33590335, 2021).
Huntington disease (17 papers, 2013 to 2024). Huntington disease (HD) is a rare neurodegenerative disorder of the central nervous system characterized by unwanted choreatic movements, behavioral and psychiatric disturbances and dementia. "For example, the reduction of HDAC4 is shown to facilitate clearance of pathogenic protein that aggregates in a Huntington disease model and antagonizes neuron degeneration." (PMID 33790287, 2021). "Recently, HDAC4 was found to be associated with aggregate-prone mutant Huntington's disease–associated products of the huntingtin gene (HTT) that have long polyglutamine stretches." (PMID 26540094, 2015). "HDAC4 associates with the aggregation-prone mutant huntingtin protein (mHTT) that causes Huntington's disease, and colocalizes with it in cytosolic inclusions." (PMID 26540094, 2015). "Class IIa selectivity is of high interest in various cases like Huntington disease, where an overexpression of HDAC4, a class IIa representative, was observed." (PMID 37570656, 2023). "Overall, the suppression of HDAC4 by miR-22 promotes neuronal survival and inhibits neurodegeneration in an in vitro model of Huntington’s disease (HD)." (PMID 36979019, 2023). "In an in-vivo model of Huntington’s disease, it was demonstrated that miR-22 targets HDAC4 and affects neuronal survival." (PMID 35842608, 2022). "Hdac4 knock-down in a mouse model of Huntington’s disease was found to delay cytoplasmic aggregates formation, restore BDNF transcript levels, and rescue neuronal and synaptic functions." (PMID 34445342, 2021). "HDAC4 is considered to be a potential therapeutic target in Huntington’s disease (HD), as a heterozygous Hdac4+/− background rescued neuronal function in a HD mouse model but has yet to be explored therapeutically in PD." (PMID 30503143, 2019). "In mouse models of Huntington's disease, HDAC4 reduction delays cytoplasmic formation of mHTT aggregates and rescues neuronal and cortico-striatal synaptic function, but does not repair the global transcriptional dysfunction." (PMID 26540094, 2015). "This reveals a new potential to treat Huntington's disease by interrupting the specific interaction between HDAC4 and MAP1S." (PMID 26540094, 2015). "HDAC4 reduction presents a novel strategy for alleviating the toxicity of huntingtin protein aggregation, thereby influencing the molecular pathology of Huntington's disease." (PMID 24302884, 2013). "Reduction of HDAC4 levels in mouse models of Huntington's disease (HD) delays cytoplasmic aggregation in the brain and improves the molecular pathology of HD, providing a potential new therapeutic target." (PMID 24302884, 2013). "Indeed, a mouse model of Huntington disease is alleviated when the levels of HDAC4 are reduced." (PMID 26055705, 2015). "Accumulation of another mHTT (GFP-HTT74Q) with a similar role as the GFPHTT72Q in Huntington's disease was observed when the GFP-HTT74Q and HDAC4 were transiently coexpressed in neuroblastoma Neuro-2a (N2a) cells." (PMID 26540094, 2015). "HDAC4 inhibition has demonstrated significant effects to increase the stability of MAP1S, MAP1S-mediated autophagy flux and degradation of mutant Huntingtin aggregates that are directly impact Huntington's disease." (PMID 27236336, 2016). "As there are currently no disease-modifying therapeutics available for Huntington's disease, we hope that this HDAC4-mediated regulation may be amenable to small-molecule therapeutics." (PMID 24302884, 2013).
Obesity (17 papers, 2013 to 2025). Accumulation of substantial excess body fat. "Decreased HDAC4 has been associated with decreased proinflammatory gene expression, insulin resistance, and obesity." (PMID 41007909, 2025). "Intriguingly, in the same subjects HDAC4 expression was restored after physical exercise, which makes HDAC4 an appealing, though potential, target for mitigating obesity-associated inflammation." (PMID 35883538, 2022). "The regulation of FoxO1 to β‐cell compensation to overnutrition and obesity was thereafter disrupted by the FoxO1 deacetylation failure in the diabetic patients harboring HDAC4 mutations." (PMID 30968599, 2019). "The pathogenic roles of HDAC4 in hyperglycemia, and/or, obesity should be thus systematically investigated in the near future." (PMID 30968599, 2019). "From this report, obesity is present in two of the three hyperglycemic families, and the detected HDAC4 variants are missense variants instead of HDAC4 haploinsufficiency." (PMID 30968599, 2019). "This is consistent with clinical data in humans that associated the haploinsufficiency of HDAC4 with obesity." (PMID 24086512, 2013). "Some top DM CpG sites are directly associated with obesity, including HDAC4 and PLEC1." (PMID 40388307, 2025). "In our study, HDAC4 and PLEC1 stand out for their strong associations with obesity-related traits among the top differentially methylated CpG sites." (PMID 40388307, 2025). "In insulin resistance induced by obesity in mice, it was found that obesity can activate CaMK II, which induced HDAC4 phosphorylation and prevented its nuclear translocation, resulting in a decrease in DACH1 expression level." (PMID 37766305, 2023). "The results revealed that 18 of the DMR genes were associated with addiction and obesity (ADCY3; ADCY9; ATF4; CDK5R1; CHRNB2; GABRD; GABRG3; GNB1; GNB3; GRK5; HDAC4; HDAC9; MAP2K1; PDE11A; PDE2A; PDE3A; PPP1CA; SLC6A3)." (PMID 34389046, 2021). "Differential methylation is found within genes associated with obesity, epigenetic regulation and development, such as CETP, FOXP2, HDAC4, DNMT3B, KCNQ1 and HOX clusters." (PMID 25651499, 2015). "Among the genes that were affected by the 2q37 deletion, the heterozygous loss of HDAC4 and CAPN4 have been suspected to cause brachydactyly and obesity, respectively, which are the most common clinical features of del2q37 syndrome." (PMID 24755370, 2014). "The decrease of HDAC4 in obese and its restoration by physical exercise is suggestive of a protective role of HDAC4 against obesity." (PMID 24086512, 2013). "In the context of obesity, HDAC4 was also recently reported to be involved in regulation of GLUT4 during adipocyte differentiation as well as promoting lypolysis." (PMID 24086512, 2013). "A study based on insulin resistance reported that CaMKII phosphorylates and blocks nuclear translocation of hepatocyte HDAC4 under conditions of obesity: lower nuclear HDAC4 decreases the SUMOylation and degradation of the co-repressor DACH1, and finally, causes defective insulin signaling." (PMID 37766305, 2023). "In summary, we detected three HDAC4 variants (de novo, and with incomplete penetrance) in three separate hyperglycemic families with/without obesity." (PMID 30968599, 2019). "Moreover, Hdac4 suppressed transcription of Glut4, a key protein for glucose uptake in adipocytes, and disruption of Hdac4 in macrophages is sufficient to promote insulin resistance and obesity." (PMID 30968599, 2019). "Consistent with a role of HDAC4 in the development of obesity, deletion in or mutation of HDAC4 was reported as resulting in reduced expression of the retinoic acid induced 1 (RAI1) gene, whose haploinsufficiency leads to obesity in SMS." (PMID 25411582, 2014). "In all patients, except one, the deletions involved HDAC4 (histone deacetylase 4), the primary causative gene for BDMR syndrome, and that could be responsible for obesity (seen in >40% of patients)." (PMID 25411582, 2014).
Obesity (continued). "In summary, our proteomic approach performed on obese humans before and after physical exercise revealed HDAC4 as target that may have a potential therapeutic benefit for the control and management of obesity and insulin resistance." (PMID 24086512, 2013). "Among the differentially expressed protein between lean and obese subjects, we focused on TSP1 and HDAC4 as they may represent potential targets against obesity." (PMID 24086512, 2013). "Together, the expression pattern of HDAC4 in obese subjects before and after physical exercise, its correlation with various physical, clinical and metabolic parameters along with its inhibitory effect on NF-κB are suggestive of a protective role of HDAC4 against obesity." (PMID 24086512, 2013). "HDAC4 could therefore represent a potential therapeutic target for the control and management of obesity and presumably insulin resistance." (PMID 24086512, 2013). "Together, our in vivo and in vitro data on HDAC4 suggest that it has a protective role against obesity and could therefore represent a potential therapeutic target for management of obesity and presumably in insulin resistance and type 2 diabetes." (PMID 24086512, 2013). "Given that HDAC4 has been shown to shuttle between nucleus and cytoplasm, we particularly analyzed whether obesity triggers a change in its cellular localization." (PMID 24086512, 2013). "Based on the negative correlation between HDAC4 levels and various metabolic and inflammatory markers and given the importance of stress kinases such as JNK, IKKβ in obesity and insulin resistance, we sought to determine whether overexpression of HDAC4 has an effect on JNK and NF-κB activation." (PMID 24086512, 2013). "In addition, are HDAC4 KO mice more prone to obesity and insulin resistance?" (PMID 24086512, 2013). "Among the proteins showing dysregulated expression by obesity that was then corrected by physical exercise, we focused on TSP1 and HDAC4 proteins for further investigations." (PMID 24086512, 2013). "However, despite these limitations, the present study showed clearly that obesity triggers differential regulation of TSP1 and HDAC4 proteins at protein and mRNA levels in both PBMCs and adipose tissue." (PMID 24086512, 2013). "In our case, HDAC4 was found mainly in the cytoplasm of PBMCs isolated from both lean and obese subjects, suggesting that obesity does not trigger any change in cellular localization of HDAC4." (PMID 24086512, 2013). "HDAC4 was further a strong candidate due to multiple affected CpG sites within the gene, and both HDAC4 and NCOR2 are biologically interesting candidates in adipose tissue and the pathogenesis of obesity and type 2 diabetes." (PMID 23825961, 2013). "Using Lamin B, Tubulin and HSF-1 as internal controls, HDAC4 was predominantly found in the cytoplasm in both groups suggesting that obesity does not trigger a change in the localization of HDAC4." (PMID 24086512, 2013).
osteosarcoma (17 papers, 2016 to 2025). A usually aggressive malignant bone-forming mesenchymal neoplasm, predominantly affecting adolescents and young adults. "HDAC4 has been implicated in osteosarcoma progression by promoting chemoresistance and enhancing cell survival, underscoring its relevance as a therapeutic target." (PMID 40332124, 2025). "In osteosarcoma, HDAC4 is highly expressed and contributes to tumor development by modulating proliferation, invasion, and apoptosis." (PMID 40332124, 2025). "Another study demonstrated that circ-LRP6 regulates the miR-141-3p/HDAC4/HMGB1 axis to contribute to osteosarcoma progression." (PMID 40696350, 2025). "Despite these insights, the precise role of HDAC4 in osteosarcoma remains poorly defined, necessitating further investigation into its expression and function in osteosarcoma tissues." (PMID 40332124, 2025). "For instance, the miR-145-3p/HDAC4 axis hampers osteosarcoma cell proliferation and promotes autophagy and apoptosis." (PMID 35936390, 2022). "For example, silencing circCRIM1 disrupted osteosarcoma cell invasion, proliferation and migration via mediation of the miR-432-5p/HDAC4 axis." (PMID 35484574, 2022). "CDKN1A was reported to interact with multiple HDACs, including HDAC4, in a human osteosarcoma cell line." (PMID 35242053, 2022). "For instance, miR-145-3p represses cell proliferation and induces autophagy and apoptosis of osteosarcoma cells through targeting HDAC4." (PMID 35936390, 2022). "For example, novel circRNA, circHIPK3 (homeodomain interacting protein kinase-3) which has been found to promote HDAC4 expression via sponging of miR-637 to regulate osteosarcoma cell proliferation, migration, and invasion." (PMID 35755302, 2022). "Few other miRNAs have been found targeting the histone modifying enzymes such as HDAC4 or Sirtuin-1 and thus inhibiting proliferation, migration, invasion and epithelial-mesenchymal transition of osteosarcoma cells, for example, miR-126, miR-133b, miR-204." (PMID 35755302, 2022). "As a result of this research, the circHIPK3/miR-637/HDAC4 axis could control the proliferation, migration, and invasion of osteosarcoma cells." (PMID 36769372, 2023). "A related study on circ_HIPK3 also demonstrated that cytoplasmic circ_HIPK3 could bind to its downstream target, HDAC4 in osteosarcoma." (PMID 36769372, 2023). "In osteosarcoma cells, HDAC4 promotes cell proliferation through the regulation of PCNA expression." (PMID 35242053, 2022). "In this context, the present study aimed to evaluate the therapeutic potential of combining doxo with the selective HDAC inhibitors, tasquinimod (Tas, targeting HDAC4) and PCI-34051 (PCI, targeting HDAC8), in SJSA-1 osteosarcoma cells." (PMID 40332124, 2025). "This study investigates the therapeutic potential of combining doxo with HDAC inhibitors, specifically Tas, an HDAC4 inhibitor, and PCI, a selective HDAC8 inhibitor, in osteosarcoma treatment." (PMID 40332124, 2025). "Circ-LRP6 sponged miR-141-3p, which resulted in higher expression of two targets of this miRNA, HDAC4 and HMGB1, and promoted the proliferation, migration, and invasion of osteosarcoma cells." (PMID 37511619, 2023). "Consequently, this study focused on the roles of HDAC4 and HDAC8 in osteosarcoma progression." (PMID 40332124, 2025). "Nevertheless, the roles of HDAC4 and PCNA in osteosarcoma (OS) remain unclear." (PMID 31552187, 2019).